TNF (tumor necrosis factor)
Diseases named in the same sentence as TNF in open-access papers (continued):
Sharing a sentence is not in itself a finding about the gene and the disease.
Stroke (continued). "It has been established that both PSD and stroke involve an increase in pro-inflammatory cytokines, in particular IL-1β, IL-6, IFN-γ and TNF-α." (PMID 33919670, 2021). "In the present study, the results of treated groups (BBR and BBR-loaded micelle) showed a significant decrease in TNF-α, IL-1ß, MDA levels in comparison with the stroke group." (PMID 34600570, 2021). "M1 is activated through the classical pathway, expressing CD16 and iNOS on cell membranes, and secretes inflammatory factors such as tumor necrosis factor-α (TNF-α) and interleukin-6 (IL-6), which exacerbate post-stroke brain injury." (PMID 33790947, 2021). "In our patients, the content of pro-inflammatory TNF-α and IL-6 was higher, and anti-inflammatory IL-10 was lower in both NWS and SWS of stroke patients." (PMID 34433866, 2021). "On the other hand, pretreated groups (@, @@) (BBR 100 mg/kg, nano BBR 100 mg/kg (p < 0.01), 75 mg/kg, and 50 mg/kg (p < 0.05)) showed a significant reduction in TNF-α, IL-1B, and MDA levels compared to the stroke group." (PMID 34600570, 2021). "In the middle cerebral artery-occlusion model, the expression of NOD2 is significantly elevated, and ablation of the NOD2 gene reduces stroke size and inflammation as indicated by lowered expression of NF-κB, MAPK, IL-6, and TNF-α." (PMID 34829993, 2021). "In our previous study, we showed that VT treatment of T1DM stroke decreases brain expression of inflammatory factors such as MCP‐1, RAGE, and TNF‐α compared to control T1DM stroke rats." (PMID 33346402, 2021). "Among the inflammatory mediators, interleukin (IL)-1β, tumor necrosis factor α (TNFα) and monocyte chemoattractant protein-1 (MCP-1) are classic factors that have been found in both experimental models and human stroke." (PMID 34327147, 2021). "Anti TNF-α (infliximab) therapy significantly enabled the preservation of BBB structure and behavioral performance in experimental stroke." (PMID 34248961, 2021). "The proinflammatory cytokines TNF-α and prostaglandin E2, which are induced during CNS diseases such as HIV, infections, stroke, Alzheimer’s disease, and multiple sclerosis, increase astrocytic Ca2+ levels and Glu exocytosis." (PMID 34445736, 2021). "Pro-inflammatory cytokines are elevated in post-mortem tissue of stroke patients, such as interleukin (IL) 6, IL-1β, interferon (IFN) γ, tumor necrosis factor (TNF) α and IL-15." (PMID 34966269, 2021). "We have demonstrated that assessment of TNF-α, IL-6, and IL-10 levels in both NWS and SWS significantly differentiates stroke patients from healthy controls." (PMID 34433866, 2021). "Nevertheless, both the concentration (pg/mL), salivary output (pg/min), and specific content (per mg protein) of TNF-α and IL-6 were significantly higher, whereas IL-10 was statistically lower in NWS and SWS of stroke patients compared to controls." (PMID 34433866, 2021). "Tumor necrosis factor (TNF) is a pleiotropic cytokine known to participate in acute stroke injury and delayed stroke recovery." (PMID 33924148, 2021). "IL-6, interleukin 1β (IL-1β) and tumor necrosis factor-alpha (TNF-α) are the major proinflammatory cytokines that provoke and aggravate an inflammatory response after stroke." (PMID 33192985, 2020). "T lymphocytes of stroke patients produced IFN-γ and TNF-α and responded to MBP peptides by increasing their production of TNF-α and IL-10 at admission, but not at later time points." (PMID 32719588, 2020). "In this study, an array of inflammatory cytokines including IL-1β, TNF-α, IL-6, cyclooxygenase (COX)-2, monocyte chemoattractant protein (MCP)-1, and chemokine (C-X-C motif) ligand 1 (CXCL1) at 6, 24, 48, and 72 h after stroke were analyzed by qRT-PCR." (PMID 32867781, 2020). "Experimental evidence shows that targeting tumor necrosis factor (TNF) and interleukin (IL)-1 holds promise, and these cytokines are considered prime targets in the development of new stroke therapies." (PMID 32503645, 2020).
Stroke (continued). "There was no change in cytokine secretion for other cytokines with cocultures of stroke-Mo and MSCs, but cocultures with healthy Mo showed a consistent decrease in secretions of IL-1RA, IL-8, MCP-1, and TNF-α." (PMID 32802081, 2020). "The data demonstrated that BR therapy significantly reduced the levels of proinflammatory cytokines interleukin (IL)-1β, IL-6, TNF-α, and the chemokine, CXCL1, at 8 h post stroke and further reduced IL-6, IFN-γ, and TNF-α at 23 h post stroke." (PMID 32843630, 2020). "Cytokines, such as interleukin-1β (IL-1β), interleukin-6 (IL-6), interleukin-8 (IL-8), tumor necrosis factor-α (TNF-α), ficolin-1 and others, have been reported to increase in relations with the incident of stroke." (PMID 33036206, 2020). "Regarding pro-inflammatory cytokines, it has been described that blocking TNF-α and IL-1β confers neuroprotection in SCI and stroke models." (PMID 31186006, 2019). "To evaluate the inflammatory responses of BDMP injection and Lactadherin treatment in stroke mice, we measured the expression of leukocytes, microglia/macrophages, neutrophils, IL1β, IL6, and TNFα in the cortex and striatum of IBZ." (PMID 31993045, 2019). "More importantly, anti-TNFα (infliximab, a potent clinically used drug) treatment significantly ameliorate endothelial necroptosis, BBB destruction and improve stroke outcomes." (PMID 31221990, 2019). "Therefore, specific inhibition of TNF‐α production by the intestinal epithelium may present a new strategy to reduce gut permeability and subsequently gut‐derived bacterial lung infection after stroke." (PMID 31199577, 2019). "Similar to the effect of miR155, an antagomir for miR210 decreased expression of proinflammatory cytokines IL6, TNFα, IL1β, CCL2, and CCL3 reducing the neurological impairment, putting miR210 as potent regulator of inflammation during stroke recovery." (PMID 31543756, 2019). "The three major proinflammatory cytokines are interleukin 1β (IL-1β), tumor necrosis factor-alpha (TNF-α), and interleukin-6 (IL-6) that provoke and aggravate an inflammatory response after stroke." (PMID 31291966, 2019). "Circulating H19 levels, which were significantly higher in 36 stroke patients compared with 25 HCs, showed a positive correlation with NIHSS scores and tumor necrosis factor-α levels." (PMID 30967760, 2019). "In summary, the major effects of MLC901 are the reduction of neutrophil recruitment, the reduction of microglia activation and the reduction of pro-inflammatory mediators (TNFα, IL6, IL1β, CCL2) production induced by stroke." (PMID 30584250, 2018). "Inhibition of TNF-α reduces ischemic brain injury, while administration of recombinant TNF-α protein after stroke onset worsens ischemic brain damage." (PMID 29540536, 2018). "To better simulate the internal environment in the brain after stroke, we applied NCM for 24 h to trigger hypoxia-ischemia in microglia and detected high levels of TNF-α in the supernatant." (PMID 29662435, 2018). "These are partly verified by our findings revealing NF-κB activation and the expression of target genes, including TNF-α, IL-1β, IL-6, iNOS, and COX-2, in KO stroke mice." (PMID 30622459, 2018). "Furthermore, we demonstrated reduced expression of genes in the spleen relating to sensing of pathogens, co-stimulation of adaptive immune responses and production of the pro-inflammatory cytokine TNFα, which may additionally contribute to impaired anti-bacterial activity after stroke." (PMID 29872438, 2018). "Indeed, elevated TNF levels are evident in many neurological disorders such as in affected areas in multiple sclerosis (MS, cf. Section 3.4.2), Alzheimer’s disease (AD, cf. Section 3.4.3), Parkinson’s disease (PD, cf. Section 3.4.4), stroke and traumatic brain injury (TBI)." (PMID 29751683, 2018).
Stroke (continued). "In cerebral ischemia/reperfusion models for stroke injury, HSP70 binds to TLR4, activating MyD88-IRAK-TRAF6 and NF-κB pathways, with downstream induction of TNFα and other cytokines, as observed for nPM-LPS responses." (PMID 28410596, 2017). "Several studies have shown that the percentages of cytotoxic T cells, natural killer (NK) cells, and B lymphocytes, and serum levels of TNF-α, IFN-γ, C-reactive protein (CRP), IL-4, IL-6, IL-10, and TGF-β are altered after stroke." (PMID 27682880, 2017). "In our study, the serum levels of TNF-α, CRP, IL-4, and IL-10 were all significantly increased in stroke patients, whereas, the serum level of IFN-γ was decreased compared with that in control subjects." (PMID 27682880, 2017). "The expression of M1 markers (TNF-α, IL-12, CD16, CD32 and iNOS) and M2 markers (Arg-1 and YM1/2) were all significantly increased in vehicle-treated stroke mice 3 days after dMCAO." (PMID 28785217, 2017). "We report that TNF‐α, IFNγ, MIP‐1α, and MCP‐1 are reduced 48 hr after stroke, supporting our previous finding that BML‐111 reduces neutrophil infiltration at 48 hr post‐stroke." (PMID 28523230, 2017). "At 48 hr post‐stroke, BML‐111 reduced levels of pro‐inflammatory cytokines TNF‐α and IFNγ compared to levels in the vehicle‐treated rats (p = .0638, p < .01, respectively)." (PMID 28523230, 2017). "TRCQT reduced brain infarct volume and improved neurological outcomes by reducing apoptosis, attenuating the expression of TNF-α and p-JNK, and reducing the formation of HO· radicals in MCAO-induced embolic stroke of rats." (PMID 28168001, 2017). "TRCQT reduced brain infarct volume and improved neurological outcomes by reducing apoptosis, attenuating the expression of TNF-α and p-JNK, and reducing the formation of hydroxyl radicals in MCAO-induced embolic stroke of rats." (PMID 28168001, 2017). "Decreased levels of serum IFN-γ and TNF-α, well known TH1 cytokines, were seen 12 h after stroke in mice." (PMID 26742037, 2016). "Sieber and collegues previously showed that increases of TNFα, IL-1β, MIP-1α, MCP-1, and IL-6 are attenuated 7 days following stroke in aged C57BL/6 mice, and that older mice have smaller infarct volumes." (PMID 27600707, 2016). "Researchers have demonstrated that the following brain insult cytokine levels are elevated as a result of increased production from inflammatory cells with IL-1, IL-6, and tumor necrosis factor-alpha (TNF-α) and being the most studied for stroke." (PMID 26074992, 2015). "Expression of TNF-α and MIP1 were significantly lower in the brains of aLA-treated rats than that in vehicle-treated rats 3 days after stroke (P < 0.05)." (PMID 25761600, 2015). "The expression of TNF-α, MIP1, Iba-1, and IL-1β were significantly lower in the aLA group than in the control group at 7 days after stroke (P < 0.05)." (PMID 25761600, 2015). "FGF and TNF-α influence the TIA and stroke occurrence, so these cytokines must participate in destabilisation of carotid plaque." (PMID 25128019, 2014). "Several signaling pathways were also involved in stroke-induced neurogenesis including Notch, retinoid, bone morphogenetic protein (BMP), tumor necrosis factor-alpha (TNF-α), and sonic hedgehog." (PMID 24719869, 2014). "miR-320 targets ETS2, a transcription factor that regulates the expression of several genes important to leukocyte extravasation post-stroke including MMP-9, MMP-3, MMP-13, ANGPT1, and TNF." (PMID 24911610, 2014). "Previous work has demonstrated that organ culture elicits an enhanced expression of TNF-α and TNFR1 both after organ culture and during in vivo stroke." (PMID 24886705, 2014). "A statistically significant correlation between stroke and the presence of TGF-β (R = 0.453), TNF-α (R = 0.624), and FGF (R = 0.476) was recorded." (PMID 25128019, 2014). "Several inflammatory genes, like interleukin-6 (IL-6), tumor-necrosis factor-alpha (TNF-α) and matrix metalloproteinase-3 (MMP-3), were also found to confer risks for stroke." (PMID 23356535, 2013).
Stroke (continued). "In SHRSP, fed a high-salt diet, rosuvastatin treatment significantly delayed the onset of stroke and attenuated the transcription of inflammatory biomarkers (MCP-1, TGF-β1, IL-1β, and TNF-α)." (PMID 23431245, 2013). "In stroke, CHIT-1, TNF-α and other pro-inflammatory cytokines are accepted as markers of microglial activation, occurring independent of pre-existing inflammatory or infectious conditions in patients." (PMID 24295388, 2013). "In SHRSP fed a high-salt diet, rosuvastatin treatment significantly delayed the onset of stroke and attenuated the transcription of inflammatory biomarkers (MCP-1, transforming growth factor-β1, interleukin (IL)-1β, and tumor necrosis factor-α (TNF-α))." (PMID 23326018, 2012). "Levels of the pro-inflammatory cytokines IL-1β, TNF-α, and IFN-γ were significantly elevated in the ischemic hemisphere considered as hallmarks of inflammation after stroke." (PMID 23028794, 2012). "Only aliskiren was able to significantly reduce stroke-induced gene expression of CXC chemokine ligand 1, interleukin-6 and tumor necrosis factor-alpha in the ischemic core." (PMID 21124781, 2010). "In support of this idea, A2A receptors have been shown to decrease TNF-α production and adhesion molecule expression following stimulation with TLR4 agonists, which are also released endogenously following stroke." (PMID 20190963, 2009). "The effects of TNF-α on adenosine receptor expression may also provide insight into the phenomenon of ischemic preconditioning, a phenomenon in which a brief noxious stimuli induce changes in the CNS and in the periphery that result in endogenous neuroprotection from stroke." (PMID 20190963, 2009). "However, hippocampal neurogenesis after ischemic injury resulting from stroke was abolished when animals were treated with anti-TNF antibodies two weeks after the ischemic event, suggesting that TNF signaling may be necessary for repair processes after an ischemic insult." (PMID 18925972, 2008). "Our findings with respect to TNF-α are consistent with one previous study, but differ from those showing that plasma or serum TNF-α concentrations after stroke are increased and correlate with cerebral infarct volume." (PMID 17328808, 2007). "This study presents a mechanistically grounded computational model that captures the nonlinear interplay between TNF-α, IL-6, and IL-10 during acute post-stroke inflammation." (PMID 41557608, 2026). "The levels of salivary TNF-α, TNF-β, IFN-γ, and IL-12 significantly differentiate ischemic stroke patients from healthy individuals, making salivary cytokines a potential biomarker for stroke." (PMID 40520895, 2025). "TLR4 has been shown to be extensively involved in stroke, myocardial infarction and inflammation, where its binding to the bridging molecules MyD88 or MAPK activates NF-κB and triggers the up-regulation of IL-1β, IL-18 and TNF-α expression." (PMID 41143181, 2025). "The positive correlation between IL-6, TNF-alpha, and NIHSS scores in our study suggests that these biomarkers are not only indicators of stroke severity but may also be utilized in the early prediction of functional outcomes." (PMID 39859987, 2025). "SPRC (ZYZ-802), by modulating CBS, reduces astrogliosis, Aβ deposition, and inflammation in Alzheimer’s disease via NF-κB/MAPK, inhibiting TNF-α, COX-2, and ERK1/2, and enhancing microglial migration through CD24 and Src/Fak/Pyk2, effects comparable to those in stroke and neuroinflammation." (PMID 41465271, 2025). "In addition, pathway analysis of our RNA-seq data revealed that TNFα signaling, IL6/STAT3 signaling, and epithelial–mesenchymal transition (EMT) gene signatures were increased in PPARα KO stroke brains." (PMID 40362325, 2025).
Stroke (continued). "In stroke mice with MCAO, M1 microglia was found to secrete inflammatory cytokines, comprising tumor necrosis factor (TNF)-α, interleukin (IL)-1β, IL-6, IL-12, and IL-23, and enhance the levels of inducible nitric oxide synthase (iNOS) and proteolytic enzymes like MMP9 and MMP3." (PMID 40556734, 2025). "In addition, TNFα can induce apoptosis in neurons and other brain cells and contribute to BBB dysfunction, thus further increasing tissue damage after stroke." (PMID 40362325, 2025). "Stroke can trigger the production of inflammatory markers such as C-reactive protein (CRP), interleukin-6 (IL-6), and tumor necrosis factor-alpha (TNF-α), which stimulate osteoclastogenesis and inhibit osteoblast function, leading to accelerated bone resorption and osteoporosis." (PMID 39792154, 2025). "Immunological and inflammatory biomarkers, including IL-1β, IL-6, TNF-α, IL-10, IL-8, IL-17, and CRP, have become indispensable tools in stroke research, offering insight into how the immune system shapes both the extent of brain injury and the trajectory of recovery." (PMID 40869247, 2025). "The level of histamine can also be upregulated by stroke in an age-dependent fashion, which was found to be correlated with the significant increase of plasma pro-inflammatory cytokines such as IL-6, granulocyte colony-stimulating factor (G-CSF), TNF-α and IFN-γ in aged stroke mice." (PMID 39351234, 2024). "The risk of major adverse cardiac events (MACEs), MI, stroke, CHF, and coronary revascularization in RA patients treated with TCZ did not exceed that in patients treated with other biologics (TNF-α inhibitors, abatacept, and rituximab)." (PMID 39596487, 2024). "Similarly, significant evaluation of IL-6,TNF-α, and IFN-γ levels has been found in PSD patients one year after stroke." (PMID 38421829, 2024). "However, in vitro analyses of human blood samples of healthy controls and stroke patients incubated with CLA showed a significantly decreased production of IFN-γ and TNF-α, and a visual decrease of IL-17A and IL-6." (PMID 39372701, 2024). "After stroke onset, activation of microglial AHR by microbial Trp-derived ligands was corroborated to suppress the expression of proinflammatory and neurotoxic genes, including TNF, IL6, IL12A, and NOS2, and boost anti-inflammatory IL10 expression." (PMID 39195495, 2024). "The equilibrium of Th1/Th2 cytokines holds paramount importance in the genesis and progression of stroke, wherein post-stroke imbalances tend to favor Th1-type responses—inclusive of IFN-γ, TNF-α, and IL-2—potentiating the exacerbation of cerebral damage and neurologic deficits." (PMID 38287458, 2024). "Stroke-induced alterations in microglia and astrocytes emerge as critical in PSD evolution, modulating neurotransmitter dynamics, neuronal viability, and cytokine release, including pro-inflammatory IL-1β, IL-6, TNF-α, and anti-inflammatory IL-10." (PMID 38377025, 2024). "However, analyses of human blood samples post-stroke showed reduced levels of pro-inflammatory interferon-γ (IFN-γ) and tumor necrosis factor alpha (TNF-α) release by T-lymphocytes following in vitro treatment with CLA." (PMID 39372701, 2024). "It is worth noting that anti-TNF therapy, used in patients to reduce inflammation and prevent strokes, does not ameliorate neutropenia." (PMID 38777862, 2024). "The most common CV events observed were nonfatal myocardial infarctions in the tofacitinib group and nonfatal strokes in the TNF-alpha inhibitors group, especially among patients aged 65 years or older." (PMID 38294723, 2024). "Furthermore, hNSC transplantation reduces infarct size and proinflammatory factor (TNF-α, IL-6, and IL-1β), matrix metalloproteinase-9 (MMP-9), and MMP-3 expression in aged stroke mice." (PMID 37728582, 2024). "TNF-α is produced by various immune cell types and is related to various physiological events, including endothelial necroptosis, breakdown of the BBB, and the results of stroke." (PMID 38756772, 2024).